CCND2-AS1 (CCND2 antisense RNA 1)
Synonyms: CCND2-AS2
Gene: Long non-coding RNA gene on chromosome 12 (4,247,981 to 4,276,265, reverse strand). Ensembl gene ENSG00000255920.
Diseases named in the same sentence as CCND2-AS1 in open-access papers:
CCND2-AS1 is named in the same sentence as 2 diseases in open-access papers, as found by Europe PMC text mining. Sharing a sentence is not in itself a finding about the gene and the disease. The quoted sentences say what the papers report.
glioma (1 paper, 2019). A benign or malignant brain and spinal cord tumor that arises from glial cells (astrocytes, oligodendrocytes, ependymal cells). "More importantly, Wnt/β-catenin was also found to interact with the lncRNA, CCND2 Antisense RNA 1 to regulate glioma cell proliferation." (PMID 31596734, 2019).
CCND2-AS1 also shares sentences with these, for which no sentence is quoted: cervical cancer (1 paper).